ZNF641 (zinc finger protein 641)
Description:
Transcriptional activator. Activates transcriptional activities of SRE and AP-1.
Synonyms: FLJ31295
Tractability: No criterion of Open Targets' tractability assessment is met for any kind of drug.
Gene: Protein-coding gene on chromosome 12 (48,337,180 to 48,351,414, reverse strand). Ensembl gene ENSG00000167528.
Subcellular location: Nucleus
Subcellular location (Human Protein Atlas): Nucleoplasm; Cytosol; Nucleoli
Pathways (Reactome):
Gene expression (Transcription): Generic Transcription Pathway
Gene Ontology:
Molecular function: DNA-binding transcription factor activity, RNA polymerase II-specific; RNA polymerase II transcription regulatory region sequence-specific DNA binding
Biological process: regulation of transcription by RNA polymerase II; regulation of DNA-templated transcription
Cellular component: nucleolus; nucleoplasm; nucleus
Genetic constraint (gnomAD): Loss-of-function variants: 23 observed, 44.4 expected, observed/expected ratio (o/e) 0.52, 90% interval 0.37 to 0.73. The upper end of that interval is the gene's LOEUF score, 0.73, which puts it in group 3 of 6, group 1 being the genes least tolerant of losing a copy. Missense variants: 461 observed, 516.11 expected, observed/expected ratio (o/e) 0.89, 90% interval 0.83 to 0.96. Synonymous variants: 155 observed, 187.24 expected, observed/expected ratio (o/e) 0.83, 90% interval 0.73 to 0.95.
Homologues: Orthologues: chimpanzee ZNF641 (99% identical), macaque ZNF641 (98% identical), dog ZNF641 (97% identical), pig ZNF641 (96% identical), rabbit ZNF641 (93% identical), guinea pig ZNF641 (90% identical), rat Zfp641 (83% identical), mouse Zfp641 (83% identical), zebrafish ovol1b (15% identical), zebrafish ovol1a (15% identical), Caenorhabditis elegans lin-48 (12% identical), Drosophila melanogaster hb (12% identical), and 5 more. Paralogues in human: OVOL1 (15% identical), OVOL2 (15% identical), PEG3 (14% identical), ZNF202 (13% identical), OVOL3 (13% identical), ZNF18 (13% identical), ZNF496 (13% identical), ZSCAN29 (13% identical), ZNF444 (13% identical), ZSCAN32 (13% identical), ZKSCAN2 (12% identical), ZBTB35 (12% identical), and 17 more.
Diseases named in the same sentence as ZNF641 in open-access papers:
ZNF641 is named in the same sentence as 5 diseases in open-access papers, as found by Europe PMC text mining. Sharing a sentence is not in itself a finding about the gene and the disease. The quoted sentences say what the papers report.
Barrett esophagus (1 paper, 2023). Esophageal lesion lined with columnar metaplastic epithelium which is flat or villiform. "EXOC3, a part of the exocyst complex, together with ZNF641, has recently been identified as a susceptibility locus for Barrett esophagus and esophageal adenocarcinoma." (PMID 37444464, 2023).
COVID-19 (1 paper, 2022). A disease caused by infection with severe acute respiratory syndrome coronavirus 2. "As examples, ZNF641 is subject to different levels of regulatory effect for each COVID-19 phenotype bin." (PMID 35995775, 2022).
hepatocellular carcinoma (1 paper, 2023). A malignant tumor that arises from hepatocytes. "HCG15 (human leukocyte antigen complex group 15) facilitates proliferation and invasion by enhancing ZNF641 transcription in hepatocellular carcinoma." (PMID 37101543, 2023).
ZNF641 also shares sentences with these, for which no sentence is quoted: esophageal adenocarcinoma (1 paper); psychosis (1).